SLC4A7 (solute carrier family 4 member 7)
Description:
Electroneutral sodium- and bicarbonate-dependent cotransporter with a Na(+):HCO3(-) 1:1 stoichiometry. Mediates the sodium-dependent bicarbonate transport important for pH recovery after acid load as well as for regulation of steady-state pH in the duodenum and vascular smooth muscle cells (By similarity). Plays a key role in macrophage acidification, mediating bicarbonate import into the cytoplasm which is crucial for net acid extrusion and maintenance of cytoplasmic pH during phagocytosis. Provides cellular bicarbonate for de novo purine and pyrimidine synthesis and is a key mediator of de novo nucleotide synthesis downstream of mTORC1 signaling in proliferating cells. [Isoform 6]: Plays a key role in macrophage acidification, mediating bicarbonate import into the cytoplasm which is crucial for net acid extrusion and maintenance of cytoplasmic pH during phagocytosis.
Synonyms: NBC2; NBC3; NBCn1; SBC2; SLC4A6
Tractability: Antibody: UniProt places it where antibodies can reach, with high confidence; its Gene Ontology location is reachable by antibodies, with high confidence; UniProt predicts a signal peptide or a membrane-spanning region; the Human Protein Atlas places it where antibodies can reach. PROTAC: ubiquitination databases record sites on it; its protein half-life has been measured.
Target class: Transporter
Gene: Protein-coding gene on chromosome 3 (27,372,723 to 27,484,451, reverse strand). Ensembl gene ENSG00000033867.
Subcellular location: Basolateral cell membrane; Apical cell membrane; Cell projection, stereocilium; Cell membrane; Cell membrane (Isoform 6)
Subcellular location (Human Protein Atlas): Plasma membrane; Cytosol; Focal adhesion sites
Pathways (Reactome):
Signal Transduction: RHOD GTPase cycle; RHOF GTPase cycle; RHOH GTPase cycle; RHOJ GTPase cycle; RHOQ GTPase cycle
Transport of small molecules: Bicarbonate transporters
Gene Ontology:
Molecular function: protein binding; sodium:bicarbonate symporter activity; monoatomic anion transmembrane transporter activity; solute:inorganic anion antiporter activity
Biological process: cellular response to growth factor stimulus; phagosome acidification; purine nucleotide biosynthetic process; pyrimidine nucleotide biosynthetic process; auditory receptor cell development; bicarbonate transport; regulation of intracellular pH; monoatomic anion transmembrane transport; monoatomic anion transport; sodium ion transmembrane transport; transmembrane transport
Cellular component: basolateral plasma membrane; membrane; plasma membrane; apical plasma membrane; stereocilium
Genetic constraint (gnomAD): Loss-of-function variants: 22 observed, 56.33 expected, observed/expected ratio (o/e) 0.39, 90% interval 0.28 to 0.56. The upper end of that interval is the gene's LOEUF score, 0.56, which puts it in group 2 of 6, group 1 being the genes least tolerant of losing a copy. Missense variants: 661 observed, 827.96 expected, observed/expected ratio (o/e) 0.8, 90% interval 0.75 to 0.85. Synonymous variants: 287 observed, 289.66 expected, observed/expected ratio (o/e) 0.99, 90% interval 0.9 to 1.09.
Homologues: Orthologues: chimpanzee SLC4A7 (99% identical), macaque SLC4A7 (98% identical), rabbit SLC4A7 (95% identical), pig SLC4A7 (93% identical), rat Slc4a7 (93% identical), dog SLC4A7 (85% identical), mouse Slc4a7 (85% identical), tropical clawed frog slc4a7 (82% identical), guinea pig SLC4A7 (79% identical), zebrafish slc4a7 (72% identical), Drosophila melanogaster Ndae1 (45% identical), Caenorhabditis elegans abts-1 (43% identical), and 2 more. Paralogues in human: SLC4A10 (65% identical), SLC4A8 (64% identical), SLC4A4 (47% identical), SLC4A5 (41% identical), SLC4A9 (35% identical), SLC4A2 (32% identical), SLC4A3 (32% identical), SLC4A1 (27% identical), SLC4A11 (18% identical).
Diseases named in the same sentence as SLC4A7 in open-access papers:
SLC4A7 is named in the same sentence as 61 diseases in open-access papers, as found by Europe PMC text mining. Sharing a sentence is not in itself a finding about the gene and the disease. The quoted sentences say what the papers report.
breast carcinoma (42 papers, 2011 to 2025). "SLC4A7 has potential as a tyrosine kinase substrate, encodes the sodium bicarbonate transporter, and also affects the intracellular pH in breast cancer." (PMID 38397135, 2024). "SLC4A7 is implicated in the pathophysiology of breast cancer and increased expression of V-ATPase correlates with cancer grade in human pancreatic intra-epithelial neoplasms and PDAC." (PMID 35401936, 2022). "Accordingly, high SLC4A7 but low SLC9A1 mRNA expression is associated with poor survival in select breast cancer molecular subtypes." (PMID 34219652, 2021). "SLC4A7 mRNA, encoding NBCn1, was expressed at the highest level in luminal A breast cancer, at intermediate level in normal-like and luminal B breast cancer, and at lowest level in HER2-enriched and basal-like breast cancer." (PMID 34219652, 2021). "The levels of SLC4A7 mRNA, encoding NBCn1, vary among breast cancer subtypes, and high SLC4A7 expression is associated with poor survival in patients with luminal A or basal-like breast cancer." (PMID 34219652, 2021). "SLC4A7 has been associated with breast cancer and hypertension, but also has been proposed to influence neurotransmitter in the brain and EF." (PMID 32019487, 2020). "MAP3K1 and SLC4A7/NEK10 were associated only with risk of PR-positive breast cancer among BRCA2 mutation carriers." (PMID 22053997, 2011). "Moreover, the germline single nucleotide polymorphism (SNP) in the NBC SLC4A7, rs4973768, is associated with increased lifetime breast cancer risk, putatively due to SLC4A7 overexpression." (PMID 37999800, 2024). "The SLC4A7 variant rs4973768 is associated with breast cancer risk." (PMID 35563727, 2022). "Notably, one of the comorbidities with significant associated pathways, breast cancer, contained SNPs affecting Solute Carrier Family 4 Member 7 (SLC4A7) and Solute Carrier Family 24 Member 3 (SLC24A3) genes." (PMID 33924631, 2021). "Based on functional genomics approaches in mice, we previously showed that the electroneutral NBCn1, encoded by the Slc4a7 gene, is predominantly responsible for the Na+,HCO3–-cotransport in breast carcinomas." (PMID 38310186, 2024). "The research has revealed that SLC4A7 promotes the occurrence and development of breast cancer, and its high expression is related to the poor prognosis of patients." (PMID 37280630, 2023). "It has been confirmed that S0859 exhibits an inhibitory effect on SLC4A7 activity in the MCF-7 human breast cancer cell line." (PMID 37894847, 2023). "It is postulated that SLC4A7 can impact breast carcinoma by acting as a modulator or a tyrosine kinase substrate through the development of carcinomas." (PMID 37894847, 2023). "Na+, HCO3- cotransporter NBCn1 (Slc4a7) is increased in ErbB2-induced breast cancer tissue compared to normal, and disrupting NBCn1 expression delays ErbB2-induced breast cancer development." (PMID 36632452, 2023). "This solution was also enriched in genes known to be associated with breast cancer susceptibility (BLM, CASP8, CASP10, DNAJC1, FGFR2, MRPS30, and SLC4A7, P-value = 3 × 10−4)." (PMID 33735170, 2021). "(A) Variation in SLC4A7 mRNA levels among patients with different breast cancer subtypes (n=135–344)." (PMID 34219652, 2021). "Even though expression of SLC4A7 mRNA was relatively low in basal-like breast cancer, we also observed a significantly worse prognosis (hazard ratio 2.14) for patients with the highest SLC4A7 mRNA levels within this breast cancer subtype." (PMID 34219652, 2021). "In fact, both SConES GS and GM selected chromosome regions related to breast cancer, like 3p24 (SLC4A7/NEK10), 5p12 (FGF10, MRPS30), 10q26 (FGFR2), and 16q12 (TOX3)." (PMID 33735170, 2021). "For example, a 2014 study showed association between breast cancer risk and seven breast cancer susceptibility loci (FGFR2, TOX3, STXBP4, SLC4A7, LSP1, 2q35, and 5p12)." (PMID 30249004, 2018).
breast carcinoma (continued). "In this light, it is interesting that heterologous expression of the Δ NErbB2 receptor in human MCF-7 breast cancer cells enhances expression of SLC4A7 and cellular acid extrusion activity." (PMID 24795638, 2014). "Particularly NBCn1 (SLC4A7) is upregulated in breast cancer cells by ErB2/HER2 oncogene and its elevated expression correlates with poor prognosis of patients with mammary tumors." (PMID 24409151, 2014). "The enhanced expression of SLC4A7 and its putative role in cellular acid extrusion would imply that SLC4A7 is involved in establishing the characteristically high pHi and low pHe observed in breast carcinomas." (PMID 24795638, 2014). "In contrast, based on tissue samples from women of European descent, we recently showed that the plasma membrane expression of SLC4A7 is upregulated in human primary breast carcinomas and metastases compared to matched normal breast tissue." (PMID 24795638, 2014). "Although the initial investigations in a population of Asian women suggested that the expression levels for SLC4A7 are reduced in breast cancer tissue compared to normal breast tissue, this has not subsequently been confirmed." (PMID 24795638, 2014). "Depleted Slc4a7-mice reveal reduced tumor growth in CAL-51 breast cancer cell line-implanted xenograft mice and thus recruited NBCn1 protein into the plasma membrane, and subsequent enhancement of bicarbonate influx is involved in de novo nucleotide synthesis and the cell growth of the tumor." (PMID 38258089, 2024). "Notably, another sodium bicarbonate cotransporter controlling acid extrusion, SLC4A7, favors tumor development and progression in breast cancer, highlighting the relevance of bicarbonate import during cancer progression." (PMID 36522548, 2022). "Indeed, we observed significantly shortened survival times (hazard ratio 2.18) for the luminal A breast cancer patients with the highest compared to the lowest SLC4A7 mRNA levels." (PMID 34219652, 2021). "The high overall SLC4A7 expression level in luminal A breast cancer argues for a prominent role of NBCn1 in this breast cancer molecular subtype and suggests that the upregulation of NBCn1 in this molecular subtype largely occurs due to transcriptional regulation." (PMID 34219652, 2021). "Finally, stimulation of full-length ErbB2 receptors in SKBr3 breast cancer cells increased both SLC4A7 expression and HCO−3-dependent pHi recovery." (PMID 24795638, 2014). "The first link between this protein and breast cancer was provided when SLC4A7 was reported to be a tyrosine kinase substrate in MCF10AT breast cancer cells and to be expressed at reduced levels in human breast cancer samples compared to matched normal breast tissue in a population of Asian women." (PMID 24795638, 2014). "Also, some meta-analysis studies found that SNPs in genes MDR, MTR, SLC4A7, ATR and CHEK1 were significantly associated with breast cancer susceptibility." (PMID 24386390, 2013). "Previously reported BRCA2-modifying alleles for breast cancer, including those in FGFR2, TOX3, MAP3K1, LSP1, 2q35, SLC4A7, 5p12, 1p11.2, ZNF365, and 19p13.1 (ER-negative only), are also associated with breast cancer risk in the general population and/or BRCA1 mutation carriers." (PMID 23544012, 2013). "However, in the MCF10AT progression model, SLC4A7 expression was approximately three times higher in low- and intermediate-grade lesions than in normal cells suggesting that at least early in breast cancer development, SLC4A7 expression may be upregulated." (PMID 24795638, 2014). "A latest study has shown that the molecular weight of NBCn1 is consistently higher in breast cancer tissues compared to that in normal tissues, suggesting a change in alternative splicing of SLC4A7 products, although it could also be due to a change in protein modification." (PMID 23409100, 2013).
breast carcinoma (continued). "Similar patterns were observed for SNPs rs3803662 in TOX3/TNRC9 and rs4973768 in SLC4A7/NEK10 in which the associations were predominantly with ER-positive breast cancer for both BRCA1 and BRCA2 mutation carriers, in line with results from studies of breast cancer in the general population." (PMID 22053997, 2011). "Net acid extrusion from breast cancer cells occurs mostly via the Na+, HCO3–-cotransporter NBCn1/SLC4A7 and Na+/H+-exchanger NHE1/SLC9A1." (PMID 37098526, 2023). "It is especially noticeable that the protein expression levels of NBCn1 and NHE1 are elevated in breast cancer tissue with HER2 overexpression or gene amplification despite low SLC4A7 and intermediate SLC9A1 mRNA levels." (PMID 34219652, 2021). "HER2-positive breast carcinomas have elevated protein expression of Na+/H+ exchanger NHE1/SLC9A1 and Na+,HCO3– cotransporter NBCn1/SLC4A7." (PMID 34219652, 2021). "We furthermore showed that Na+, HCO−3 cotransport of low sensitivity to DIDS, a hall-mark of epithelial SLC4A7-mediated HCO−3 transport, is the predominant mechanism of acid extrusion in freshly isolated slices of human primary breast carcinomas." (PMID 24795638, 2014). "One of the important players in corresponding pH regulation is the electroneutral Na+, HCO−3 cotransporter (SLC4A7, NBCn1), which is significantly over-expressed in human mammary carcinomas." (PMID 25988147, 2014). "Besides, even protein-coding genes linked to breast cancer susceptibility, like NEK10 (P-value 1.6 × 10-5, overlapping with SLC4A7) or POU5F1B, were absent from the PPIN." (PMID 33735170, 2021).
Hypertension (12 papers, 2013 to 2025). The presence of chronic increased pressure in the systemic arterial system. "Dysfunction of SLC4A7 is implicated in renal sodium retention and the subsequent development of hypertension." (PMID 40863220, 2025). "Others have shown that NBCn1 is involved in the regulation of the contraction of blood vessel smooth msucle, indicating the presence of a cardiovascular component in the development of hypertension caused by the dysfuction of SLC4A7." (PMID 37082243, 2023). "The inhibitory role of NBCn1 and AE2 in renal sodium reaborption indicates that the development of hypertension associated with the dysfunction of SLC4A7 and SLC4A2 could be the result of renal sodium retention." (PMID 37082243, 2023). "Dysfunctions of SLC4A2 encoding AE2 and SLC4A7 encoding NBCn1 are associated with hypertension." (PMID 37082243, 2023). "Several gene regions identified in this study were near previously implicated hypertension genes (eg, GRM7, SLC4A7, ADAMTS9)." (PMID 26866891, 2016). "However, generalization of previously implicated hypertension (GRM7, SLC4A7, ADAMTS9) and SBP-associated loci (PLEKHA7) from cross-sectional analyses with much larger sample sizes, provide strong evidence that these statistical models are robust." (PMID 26866891, 2016).
triple-negative breast carcinoma (4 papers, 2015 to 2024). An invasive breast carcinoma which is negative for expression of estrogen receptor (ER), progesterone receptor (PR), and human epidermal growth factor receptor 2 (HER2). "Our previous studies found that SLC4A7 mRNA expression levels predict survival specifically in patients with luminal A and basal-like/triple-negative breast cancer." (PMID 38310186, 2024). "Accordingly, we observe reduced survival for patients suffering from luminal A or basal-like/triple-negative breast cancer with high SLC4A7 and/or low SLC9A1 mRNA expression." (PMID 34219652, 2021). "Nonetheless, the survival of triple-negative breast cancer patients is sensitive to variation in SLC4A7 transcript levels most likely due to high proliferative and metabolic activities that challenge pHi homeostasis." (PMID 34219652, 2021). "This is particularly evident in triple-negative breast cancer that shows an overall low expression of SLC4A7 mRNA." (PMID 34219652, 2021).
Blindness (3 papers, 2016 to 2021). Blindness is the condition of lacking visual perception defined as a profound reduction in visual perception. "Normal vision in NBCn1 KO mice contrasts with the early report of selective loss of photoreceptor cells and blindness caused by Slc4a7 gene knockout." (PMID 33321164, 2021). "Interestingly, mice lacking SLC4A7 develop blindness and auditory impairment due to the degeneration of sensory receptors in the eye and inner ear." (PMID 28934248, 2017).
head and neck squamous cell carcinoma (3 papers, 2023 to 2025). A squamous cell carcinoma that arises from any of the following anatomic sites: lip and oral cavity, nasal cavity, paranasal sinuses, pharynx, larynx, and salivary glands. "Further supporting this mechanism, sodium bicarbonate cotransporter 3 (SLC4A7)PAK5 (P21 (RAC1) Activated Kinase 5) has been implicated in EMT induction and metastatic behavior in head and neck squamous cell carcinoma (HNSCC)." (PMID 40740483, 2025). "Furthermore, SLC4A7 can impact the progression of head and neck squamous cell carcinoma (HNSCC)." (PMID 37894847, 2023).
breast tumor (2 papers, 2018 to 2025). "A major plasma membrane ion transport protein in breast tumors, which was identified by functional genomics analyses, is NBCn1 (SLC4A7), that loads base equivalents into cells thereby elevating pHi while acidifying the extracellular environment." (PMID 41219199, 2025).
colorectal cancer (2 papers, 2014 to 2023). A primary or metastatic malignant neoplasm that affects the colon or rectum. "In Affymetrix primeview human GeneChip array, we found six upregulated genes (STAT1, ATF2, TNFRSF10B, TGFBR2, BAX, and SQSTM1) and two downregulated genes (SLC4A7 and CD274) related to apoptosis and proliferation of colorectal cancer cells after hsa_circ_0064559 knockdown." (PMID 37280630, 2023).
melanoma (2 papers, 2019 to 2025). A malignant, usually aggressive tumor composed of atypical, neoplastic melanocytes. "Alterations in 3′ UTRs, such as the NBCn1 (SLC4A7) SNP rs4973768, have been linked to increased cancer risk, suggesting a possible contribution to melanoma susceptibility." (PMID 41465101, 2025).
pancreatic ductal adenocarcinoma (2 papers, 2022 to 2024). An infiltrating adenocarcinoma that arises from the epithelial cells of the pancreas. "Recent studies have implicated SLC4A7 in tumor growth by inducing micropinocytosis in SLC4A7 knockout Ras mutant pancreatic ductal adenocarcinoma (PDAC) cells." (PMID 38534987, 2024).
atherosclerosis (1 paper, 2021). A disease characterized by the build-up of fatty material and calcium deposition in the arterial wall resulting in partial or complete occlusion of the arterial lumen. "Integrating miRNA measurements with mRNA, we identified 27 target genes including SLC4A7, a critical sodium and bicarbonate transporter, that are potentially dysregulated during atherosclerosis." (PMID 33547350, 2021).
corneal dystrophies (1 paper, 2013). "Given the known involvement of SLC4A4 and SLC4A11 in corneal dystrophies, we speculate that the other two highly expressed genes in the uncultured corneal endothelium, SLC4A2 and SLC4A7, are worthy of being considered as potential candidate genes for corneal endothelial diseases." (PMID 23734078, 2013).
gastric cancer (1 paper, 2023). A primary or metastatic malignant neoplasm involving the stomach. "The parent gene of circSLC4A7, SLC4A7, showed a higher expression level in 3 gastric cancer cells (AGS, MGC803, and SGC7901) than in GES1." (PMID 37474578, 2023).
glioma (1 paper, 2026). A benign or malignant brain and spinal cord tumor that arises from glial cells (astrocytes, oligodendrocytes, ependymal cells). "Potential glioma risk genes with a pathogenic GV most frequently played roles in cell adhesion (CTNND1, EPCAM), immune response (IFIH1, SAMHD1), and ion transport (SLC4A7, TRPM1)." (PMID 41546701, 2026).